CD4 (CD4 molecule)
Diseases named in the same sentence as CD4 in open-access papers (continued):
Sharing a sentence is not in itself a finding about the gene and the disease.
COVID-19 (continued). "However, the patient with myopericarditis after COVID-19 vaccine exhibited an increase of terminally differentiated effector memory CD4+ T cells expressing CD45RA (TEMRA; CCR7-CD45RA+) compared with both healthy and vaccinated controls." (PMID 35251049, 2022). "Despite recommendations for additional COVID-19 vaccine doses being based in part on CD4 cell count, we identified that the proportion of PWH who received additional doses was low, varied little by CD4 cell count, and was likely associated with clinical decision-making and patient preference." (PMID 36227594, 2022). "Additionally, NK cell-based therapy strategies, have now received attention to hopefully control the harmful cytokine storm induced by SARS-CoV-2 activation of infected macrophages and CD4+ T cells in severe COVID-19 patients." (PMID 35197972, 2022). "Deep immunodepression and low CD4 count could therefore increase the probability of having lymphopenia and a pejorative course of COVID-19 in HIV patients." (PMID 35031068, 2022). "As a consequence, the COVID-19 vaccines-induced CD4+ T cell responses may play an important role in protection against hospitalization or death." (PMID 35844601, 2022). "Because higher levels of sFasL in the plasma of hospitalized COVID-19 patients correlate with the extent of CD4 T-cell apoptosis, we assessed the levels of sFasL in S-flow responders and nonresponders (not all patients were tested due to the limited available samples)." (PMID 36030261, 2022). "In addition, they did not focus on such factors as the presence of radiological changes in imaging testing, being on cART, or lymphocyte CD4+ count, which we found affected the outcome of COVID-19." (PMID 35632714, 2022). "More severe COVID-19 induced a stronger SARS-CoV-2-specific CD4+ T cell response." (PMID 35185909, 2022). "Collectively, our data indicate an imbalance in CD4+ T cell profiles during pediatric COVID-19 that might favor the course of inflammatory processes." (PMID 35663467, 2022). "Importantly, none of the HIV-related variables contributed significantly to COVID-19 vaccine willingness, including participants' CD4 level, HIV viral load status, or time living with HIV." (PMID 35847816, 2022). "Indeed, persistent activation of CD4+ and CD8+ T cells in COVID-19 patients is associated with severe disease and worse outcomes." (PMID 35572514, 2022). "Moreover, activated CD4+ T cells in severe COVID-19 patients expressed higher levels of CD25, while suppressing the expression of FoxP3, resulting in a disrupted FoxP3-mediated mechanism in the lung." (PMID 35497875, 2022). "Besides, CKD is associated with higher pro-inflammatory serum cytokines levels and CD4+T lymphocytes in hospitalized COVID-19 patients." (PMID 36553678, 2022). "We found only minor differences in the transcriptome and DNA methylation profiles of immune cells in convalescent COVID-19 individuals, and these differences were consistently more pronounced in monocytes and CD4+ T cells compared to other immune cell populations." (PMID 35464396, 2022). "Inflammatory CD4+ Th17 cells have been shown to mediate lung damage in COVID-19 patients." (PMID 35757734, 2022). "However, it is difficult to classify the mild and severe COVID-19 patients based on CD4+ T cells and CD8+ T cells." (PMID 35601483, 2022). "However, the longevity of the response of CD4+ T-cells and if a higher T-cell response confers protection from COVID-19 is still being investigated." (PMID 36423026, 2022). "Viral load testing and CD4 counts have been disrupted during COVID-19." (PMID 36408047, 2022). "Moreover, COVID-19 can be more severe in patients who arrive at the hospital with low CD4+ and CD8+ T cell numbers, which can lead to worse clinical outcomes." (PMID 35432324, 2022).
COVID-19 (continued). "Among PLWH who were naive to COVID-19 at study entry, we observed a weak positive correlation between recent CD4+ T-cell count and viral neutralization activity after one dose (Spearman’s ρ = 0.21, p = 0.04), but this association no longer remained at either time point after two doses." (PMID 35228535, 2022). "Although these laboratory and radiological findings, such as lower CD4 counts, and brain abnormalities may hint the possible cryptococcosis in patients with COVID-19, some radiological findings, such as hydrocephalus could be delayed findings." (PMID 36294675, 2022). "Likewise, the reduction in the proportion of CD3 cells in severe COVID-19 patients is not only related to a decrease in the proportion of CD8 cells but also to a mild decrease in the proportion of CD4 cells and a significant decrease in MAIT cells." (PMID 35743021, 2022). "Likewise, celecoxib and aspirin, two COX-inhibitors widely used in COVID-19 patients, can increase PD-1 expression in CD4+ and CD8+ chimeric antigen receptor T cells in vitro." (PMID 35860236, 2022). "Severe COVID-19 illness was associated with a more diverse CD4+ T cell response to SARS-CoV-2 both prior to and after mRNA vaccination, suggesting imprinting of CD4+ T cells by severe infection." (PMID 36263073, 2022). "DC has a major role in T cell responses (CD8+ and CD4+ T cell population) in COVID-19 patients." (PMID 35222380, 2022). "Enhanced lymphocyte cytotoxicity and CD4+ macrophage infiltration in fatal COVID-19." (PMID 35446789, 2022). "Hence, IDE surface expression was much higher on the monocytes and CD4+ T-cells (both as percentages and MFIs), and partially on the CD4− T-cells (only as percentages), from female post-COVID-19 patients compared to their male counterparts." (PMID 36232381, 2022). "To obtain a complete picture of the adaptive immune response to anti–COVID-19 vaccination, we evaluated the antigen-specific CD4+ T cell response to SARS-CoV-2 spike protein peptides, monitoring CD154 expression and the production of IL-2, IFN-γ, and TNF-α upon in vitro stimulation." (PMID 35139036, 2022). "In addition, studying CD4:CD8 ratios showed that COVID-19 patients had a similar CD4:CD8 ratio (1.5), when compared with the HS (1.6) and the VS (1.7) (p> 0.05)." (PMID 35898494, 2022). "Therefore, our data propose that a highly functional CD4+ T cell response persists in COVID-19 convalescent individuals and possibly contributes to immune-mediated long-term protection." (PMID 35336918, 2022). "A recent study also showed the level of decreased CD4 + T cell may prompt the severity of CT imaging in patients with COVID-19." (PMID 35197947, 2022). "We found that increased pSTAT3 levels in both CD4 and CD8 T cells was associated with decreased production of IFN-γ in response to CD3/CD28 stimulation, suggesting increased STAT3 activation as a mechanism for defects in T cell function during COVID-19." (PMID 35421120, 2022). "Thus, despite the reduced CD4+ T cell count in the peripheral blood of PLWH, the CD4+ cellular response to COVID-19 vaccination is preserved." (PMID 36532034, 2022). "The COVID-19 severity has been correlated with several granular parameters of immature neutrophils, dysregulated myeloid cell compartments, and increased proliferative CD4+ and CD8+ T cells with heightened cytokine storm." (PMID 36072602, 2022). "An increase in gene pathways involved with an adaptive immune response and increase in predicted CD4+ and CD8+ T cells and naïve B cells was detected and associated with young COVID-19 survivors, highlighting the importance of an efficient adaptive immune response as previously reported." (PMID 35663963, 2022). "This aspect revealed clonal expansion of unique but unshared CD4 T-cell clones in COVID-19 CSF." (PMID 36365007, 2022).
COVID-19 (continued). "As depletion of CD4+ T cells was shown to be associated with worse COVID-19 disease outcome, PLWH with low CD4+ cell count could have aggravated COVID-19 disease progression due to synergic effect of the two viruses." (PMID 34843064, 2022). "In contrast, the M protein-specific CD4+ TCLs had a transcriptomic signature of marked suppression of STAT1-IFRs-interferon pathway signaling, a signature that is virtually indistinguishable from the molecular signature seen associated with severe COVID-19." (PMID 35844575, 2022). "Regarding caspase targeting agents, the pan-caspase inhibitor Emricasan (EMR) was shown to attenuate caspase-1 hyperactivity in CD4+ T cells from COVID-19 patients ex vivo and the caspase-8 inhibitor Z-IETD-FMK subdued SARS-CoV-2-induced BID cleavage and caspase-3 activation." (PMID 35265086, 2022). "This study focuses on the relationship between SARS-CoV-2-specific CD4+ T cells and antibody responses that persist following COVID-19, which were assessed during the first wave of infections in Boston, Massachusetts, United States, in individuals prior to vaccination." (PMID 35857584, 2022). "Later, it was demonstrated that the treatment of leronlimab antibody (CCR-5 blocker) restores the levels of CD4+ and CD8+ T cells, reduces plasmatic IL-6, and decreases the SARS-CoV-2 viremia." (PMID 35062298, 2022). "In recuperating COVID-19 patients, a pattern of antigen immunodominance has been observed where nine viral proteins are shown to be responsible for 83% of total CD4+ T lymphocyte response and eight viral proteins are responsible for 81% of total CD8+ T lymphocyte response." (PMID 36298504, 2022). "On the other hand, a recent study of the Tregs (CD4+ FoxP3+ CD25+) in PBMC of COVID-19 patients treated in intensive care units showed a significant decrease in Treg numbers and a similar decrease in the expression of FoxP3 mRNA and immunosuppressive cytokines (IL-10 and TGFβ)." (PMID 36362440, 2022). "Controversially, the rapid induction of humoral response and the prolonged absence of SARS-CoV-2-specific CD4+ T cells were linked with an increase in disease severity and poor COVID-19 outcomes." (PMID 35337103, 2022). "Importantly, all the CD4+ T cells subsets enriched in severe COVID-19 alter the Th1-induced antiviral defenses." (PMID 36678366, 2022). "Likewise, as in memory CD4+ T cells, the frequency of PD-1 expressing cells were reported to be higher after one month in recovered patients with severe COVID-19, and correlated with the age of the patient." (PMID 35833134, 2022). "Furthermore, we demonstrate that the levels of CD4 T-cell death and soluble Fas ligand (sFasL) correlate with weaker IgG responses in COVID-19 individuals." (PMID 36030261, 2022). "Peripheral CD4+ T cell subsets are correlated with COVID-19 severity." (PMID 36146627, 2022). "Within this co-expression network, we found that except for CD4+ T-cell count, all of the T-cell markers (T-cell count, percent, ratio) were negatively or positively correlated with ten urine microbial metabolites in COVID-19." (PMID 35422810, 2022). "Our results with H1N1Ag or PfAg further support the hypothesis that the observed modulation of SARS-CoV-2-reactive CD4+ and CD8+ T cells in samples from COVID-19 patients is associated with helminth intrinsic immune regulatory properties." (PMID 35764965, 2022). "Furthermore, the connectivity of genes in module 4 of the healthy network from CD4+ T cells gradually decreases with the progression of COVID-19." (PMID 35601483, 2022). "Our results add to a growing body of evidence that adult PLWH receiving stable antiretroviral therapy, who have suppressed plasma HIV loads and who have CD4+ T-cell counts in a healthy range, generally mount robust initial humoral immune responses to two COVID-19 vaccine doses." (PMID 35228535, 2022).
COVID-19 (continued). "Disrupted antigen presentation and antibody response were also observed during COVID-19 from an increased expression of FAS receptors (pro-apoptotic molecules) in CD4+ T and CD8+ T cell populations as well as B cell populations (Naïve B cell, class-switched memory B cell)." (PMID 36532041, 2022). "Accordingly, it has been pointed out that the amount of CD4+ cells having the ability to recognize only the S protein of COVID-19 is lower than those considered to be cross-reactive to other proteins of COVID-19 among unexposed individuals, being 35% and well over 40%, respectively." (PMID 35562685, 2022). "However, several very recent reports show that both CD4+ TH and CD8+ TC cell responses are adequately maintained against the Omicron variant after vaccination and recovery from COVID-19." (PMID 35632675, 2022). "In other words, the strength of collected immune activities of these genes from CD4+ T cells may be lower and lower with the development of COVID-19." (PMID 35601483, 2022). "In vitro experimental studies showed that pan-caspase inhibitor emricasan (EMR) could reduce active caspase-1 in CD4+ T cells from COVID-19 patients." (PMID 36263178, 2022). "The following basic demographic, clinical, and laboratory test information were collected for each patient: age, race/ethnicity, gender, CD4/viral load count before and after COVID-19 diagnosis, clinical symptoms, hospitalizations, antiretroviral medications, and comorbidities." (PMID 35371792, 2022). "Studies in adult populations that have included convalescent time points demonstrate that about 70%–90% of adults with COVID-19 have detectable CD4+ and CD8+ T cell responses 1 month after symptom onset, which is remarkably similar to what we found in children." (PMID 35044955, 2022). "T-cell studies on patients with mild versus severe COVID-19 have in both cases shown a robust specific T-cell response (both CD4+ and CD8+ T-cells) but the T-cell phenotypes (e.g., cytokine production and dominant T-cell subset) differ between the two disease severity groups." (PMID 35743491, 2022). "In addition, COVID-19 patients with severe conditions had lower counts of these cells than patients with mild conditions (p = 0.0008 for CD4 + T lymphocytes, p = 0.0002 for CD8 + T lymphocytes, and p = 0.0069 for NK cells)." (PMID 35842705, 2022). "However, in the acute phase of the disease the majority of SARS-CoV-2-specific CD4+ T cells in COVID-19 convalescents were identified as central memory T cells." (PMID 36146622, 2022). "Similarly, the proportion of γδ T cells expressing CD4 was increased in COVID-19 compared to healthy donors, while frequency of CD8 γδ T cells remained unchanged." (PMID 36032159, 2022). "Therefore, COVID-19 patients were characterised by CD4+ T-cell lymphopenia and their white blood cell differentials were skewed towards higher neutrophil and immature granulocyte percentages and lower lymphocyte percentages." (PMID 35980979, 2022). "Irrespective of the antihypertensive treatment use, including ACEi or ARB, our cohort showed significantly (bonferroni corrected P significance) reduced levels of naïve CD8 + and CD4 + T cells compared to healthy donors, which is consistent with the severe T cell depletion in COVID-19 patients." (PMID 36817759, 2022). "In a French study, a low dose of dexamethasone in COVID-19 patients with ARDS was associated with more profound immune dysfunction on day 1 (lower expression of HLA-DR on monocytes and lower CD4+ cell counts) but also prevented fever and shortened the mechanical ventilation duration." (PMID 35392095, 2022). "TREM-2–Fc fusion protein, used to block the interaction between TREM-2 and M protein, reduced the phosphorylation of CD3ζ (Tyr83) and ZAP70 (Tyr319) in CD4+ T cells of patients with COVID-19 upon pseudovirus–M protein stimulation, whereas control IgG did not affect the phosphorylation of CD3ζ/ZAP70." (PMID 34878838, 2021).
COVID-19 (continued). "Notably, we observed an overall reversal of the COVID-19 serum–induced increase in costimulatory and exhaustion marker expression on both CD4+ and CD8+ T cells following addition of blocking antibodies to cell cultures." (PMID 34784300, 2021). "Interestingly, aberrant pathological cytotoxic T cells derived from CD4+ T cells are noted among severe COVID-19 patients." (PMID 33390800, 2021). "In addition, lower values of T lymphocytes and their subsets (total CD3+ <200/μL, CD4+ <100/μL and CD8+ <100/μL) are significantly associated with a higher risk of hospital death due to COVID-19." (PMID 33669527, 2021). "Indeed, more severe forms of COVID-19 correlate with the SARS-CoV-2–specific CD4 response, displaying a limited capacity to produce IFN-γ, reduced expression of GrB and Ki-67, and elevated expression of HLA-DR." (PMID 33945513, 2021). "However, we found the T-helper 1 subset (defined as CD4+ T cells secreting IFN-γ) significantly decreased when comparing all COVID-19 patients to healthy controls." (PMID 34226537, 2021). "The MAFF-promoter region showed increased accessibility in acute COVID-19 monocytes in comparison to monocytes from post-COVID-19 and HC subjects, whereas CD4 chromatin opening was reduced in monocytes from the acute disease, intermediate in post-COVID-19 monocytes and maximum in HC." (PMID 34572439, 2021). "Therefore, we next characterized CD4+ T cell immunity to HCoV spike in unexposed individuals and COVID-19 convalescents." (PMID 34465633, 2021). "Interestingly, it is evident in severe patients contracted with COVID-19 that CD4+ T and CD8+ T levels were low." (PMID 34295314, 2021). "Thus, all of the convalescent donors who recovered from COVID-19 generated CD4+ T and CD8+ T-cell responses against SARS-CoV-2 within the memory CD45RA– T-cell population." (PMID 33718360, 2021). "Adding the percentage of VDAC1+CPT1a+ myeloid cells, pDCs, and H3K27Me3+VDAC1+CD4+ improved prediction of COVID-19 severity compared with basic clinical information, highlighting the important contribution of the immune cell populations identified to disease severity." (PMID 33691089, 2021). "Patients with critical COVID-19 had levels of peripheral CD4+ T cells that were reduced 3.1-fold in comparison with mild COVID-19 (p<0.01) and healthy donors (p<0.05), whereas the levels of Tregs were increased 2.7-fold in these patients (p<0.05 regarding healthy donors)." (PMID 34122423, 2021). "As expected, the expression of HLA-DR, CD38, and Ki67 on SARS-CoV-2–responding CD4+ T cells was significantly higher in COVID-19 cases compared with non–COVID-19 controls (P = 0.005, P < 0.0001, and P = 0.004, respectively), likely reflecting ongoing viral replication." (PMID 33945513, 2021). "In addition, it has been reported that spike protein-specific memory B cell differentiation and antibody affinity maturation in mildly recovered COVID-19 and severely ill patients correlate well with the function of IL-21-producing CD4+ T cells." (PMID 34502427, 2021). "Notably, it was observed that S2-reactive CD4+ T cells from both COVID-19 patients and healthy donors exhibited a memory phenotype and significant TH1 polarization, characterized by the expression of IFNɣ." (PMID 33672450, 2021). "The numbers of CD3+ T cells (area under curve (AUC) =0.980), CD4+ T cells (AUC=0.972), and CD8+ T cells (AUC=0.933) provided a diagnostic value by identifying severe COVID-19 patients with high sensitivity and specificity, of whom the cut-off values were 575, 392, 214 cells/μL, respectively." (PMID 34766001, 2021). "In contrast, mild COVID-19 patients displayed increased ICOS-1 expression on CD4+T cells." (PMID 33692788, 2021). "Thus, we examined the CD4+ T cell reactivity in unexposed donors and the patients recovered from mild COVID-19." (PMID 33777028, 2021).